LINC01164 (long independently transcribed non-coding RNA 1164)
Gene: Long non-coding RNA gene on chromosome 10 (131,772,383 to 131,790,199, reverse strand). Ensembl gene ENSG00000189275.
Diseases named in the same sentence as LINC01164 in open-access papers:
LINC01164 is named in the same sentence as 3 diseases in open-access papers, as found by Europe PMC text mining. Sharing a sentence is not in itself a finding about the gene and the disease. The quoted sentences say what the papers report.
lung adenocarcinoma (1 paper, 2024). A carcinoma that arises from the lung and is characterized by the presence of malignant glandular epithelial cells. "The ceRNA mechanism, involving genes like TENM4, XRCC2, HDAC5, CDKN1A, ARFGEF3, SNAP25-AS1, RP11-58O9.2, LINC01164, VLDLR-AS1, and RP11-14I17.2, may play a role in lung adenocarcinoma (LUAD) development linked to tumor hypoxia." (PMID 39236027, 2024).
lung carcinoma (1 paper, 2024). "Our findings suggest a potential involvement of SNAP25-AS1, RP11-58O9.2, TENM4, XRCC2, LINC01164, VLDLR-AS1, RP11-14I17.2, and CDKN1A in the development of hypoxia-induced lung cancer." (PMID 39236027, 2024).
LINC01164 also shares sentences with these, for which no sentence is quoted: tumor (1 paper).